CER1 (cerberus 1, DAN family BMP antagonist)
Description:
Cytokine that may play a role in anterior neural induction and somite formation during embryogenesis in part through a BMP-inhibitory mechanism. Can regulate Nodal signaling during gastrulation as well as the formation and patterning of the primitive streak (By similarity).
Synonyms: DAND4
Tractability: Antibody: UniProt places it where antibodies can reach, with high confidence; its Gene Ontology location is reachable by antibodies, with high confidence; UniProt predicts a signal peptide or a membrane-spanning region.
Gene: Protein-coding gene on chromosome 9 (14,719,724 to 14,722,733, reverse strand). Ensembl gene ENSG00000147869.
Subcellular location: Secreted
Pathways (Reactome):
Developmental Biology: Developmental Lineage of Multipotent Pancreatic Progenitor Cells; Regulation of signaling by NODAL; Signaling by NODAL
Signal Transduction: Signaling by BMP
Gene Ontology:
Molecular function: BMP binding; morphogen activity; protein sequestering activity; receptor ligand inhibitor activity; protein homodimerization activity
Biological process: bone mineralization; determination of dorsal identity; negative regulation of activin receptor signaling pathway; negative regulation of BMP signaling pathway; negative regulation of mesoderm development; nervous system development; anterior/posterior axis specification; anterior/posterior pattern specification; cell migration involved in gastrulation; determination of heart left/right asymmetry; gastrulation; growth plate cartilage chondrocyte proliferation; negative regulation of cell population proliferation; negative regulation of Wnt signaling pathway; signal transduction involved in regulation of gene expression; ureteric bud development; animal organ development; regionalization; system development; tissue development
Cellular component: extracellular region
Genetic constraint (gnomAD): Loss-of-function variants: 13 observed, 14.21 expected, observed/expected ratio (o/e) 0.91, 90% interval 0.59 to 1.45. The upper end of that interval is the gene's LOEUF score, 1.45, which puts it in group 5 of 6, group 1 being the genes least tolerant of losing a copy. Missense variants: 431 observed, 342.81 expected, observed/expected ratio (o/e) 1.26, 90% interval 1.16 to 1.36. Synonymous variants: 141 observed, 128.85 expected, observed/expected ratio (o/e) 1.09, 90% interval 0.95 to 1.26.
Homologues: Orthologues: chimpanzee CER1 (98% identical), macaque CER1 (94% identical), dog CER1 (79% identical), rabbit CER1 (79% identical), pig CER1 (74% identical), guinea pig CER1 (72% identical), mouse Cer1 (69% identical), rat Cer1 (68% identical), tropical clawed frog cer1 (29% identical). Paralogues in human: DAND5 (19% identical).
Diseases named in the same sentence as CER1 in open-access papers:
CER1 is named in the same sentence as 14 diseases in open-access papers, as found by Europe PMC text mining. Sharing a sentence is not in itself a finding about the gene and the disease. The quoted sentences say what the papers report.
trigonocephaly (3 papers, 2013 to 2023). "It is hypothesized that defects in the CER1 gene may play a role in the trigonocephaly phenotype, but several recent studies have disproved this." (PMID 23984121, 2013). "Although CER1 and FREM1 (OMIM# 608944) were suggested as responsible for trigonocephaly, in our patient 8, who had trigonocephaly, the CER1 and FREM1 loci were not part of the deleted 9p region." (PMID 34609792, 2021). "According to the literature, CER1 and FREM1 have been suggested as responsible for trigonocephaly, DOCK8 has been proposed as a candidate gene for mental retardation and seizures, FOXD4 has been related to speech and language delay, and DMRT1 may play a role in sex reversal." (PMID 36672887, 2023). "This suggests that CER1 and FRM1 are not the only genes responsible for trigonocephaly and that other distal genes may be responsible." (PMID 34609792, 2021).
glioma (2 papers, 2019 to 2024). A benign or malignant brain and spinal cord tumor that arises from glial cells (astrocytes, oligodendrocytes, ependymal cells). "Higher expressions of CER1 and FSTL1 were associated with poor survival and early glioma recurrence." (PMID 38672212, 2024). "The expression of four genes (CER1, FRAT1, FSTL1, and RPSA) involved in the Wnt/β-catenin pathway was significantly associated with mortality and disease progression in patients with glioma, especially in those with grade III glioma." (PMID 38672212, 2024). "In contrast, if the actions of FRAT1 and BMP2 become stronger and those of FSTL1 and CER1 become weaker in patients with grade III gliomas, the difference in survival and disease progression between these opposing groups may significantly increase." (PMID 38672212, 2024). "Based on our findings, we hypothesized that the effects of FSTL1 and CER1 in grade III gliomas are stronger, whereas those of FRAT1 and BMP2 are weaker." (PMID 38672212, 2024). "Therefore, we believe that similarly to FSTL1, CER1 may also inhibit the activation of the BMP2 pathway, which would induce undifferentiation of glioma cells and cause poor prognosis in patients with glioma." (PMID 38672212, 2024). "Our study also showed that the expression of genes associated with poor prognosis in gliomas, such as FSTL1 and CER1, was significantly higher in grade III than in grade II gliomas." (PMID 38672212, 2024). "When the study patients were classified according to the WHO grade, CER1 and FSTL1 showed significantly higher expression, while FRAT1 showed significantly lower expression in patients with grade III glioma than in patients with grade II glioma." (PMID 38672212, 2024). "In addition, the overexpression of CER1, a BMP antagonist, inhibits BMP2 to induce undifferentiated glioma cells." (PMID 38672212, 2024).
osteoporosis (2 papers, 2013 to 2022). A condition of reduced bone mass, with decreased cortical thickness and a decrease in the number and size of the trabeculae of cancellous bone (but normal chemical composition), resulting in increased fracture incidence. "In our study, we focused on the effects of polymorphisms in CER1 and DKK1 genes, recently reported as important susceptibility genes for osteoporosis, on bone mineral density (BMD) and bone markers in osteoporotic women." (PMID 24138842, 2013). "Follow-up measurements in osteoporotic patients' serum samples, after 6 months and 1 year of fracture or starting therapy, will possibly show a stronger correlation with the CER1 gene, leading to a new insight into personalized therapy of osteoporosis." (PMID 24138842, 2013). "In our study, we investigated the possible association of two important susceptibility genes for osteoporosis, DKK1 and CER1, that participate in Wnt and TGFbeta signaling pathways, respectively, and are known for their functional role in bone mass regulation." (PMID 24138842, 2013). "The human cerberus 1, DAN family BMP antagonist gene (CER1; NM_005454.2), a candidate gene for osteoporosis located in 9p23-p22, belongs to a distinct group of BMP antagonists (ligand traps) that can bind directly to BMPs and inhibit their activity." (PMID 24138842, 2013). "In further GWAS, both the studied CER1 and DKK1 variations should be included in order to evaluate their biological role in osteoporosis." (PMID 24138842, 2013).
Allergy (1 paper, 2017). An allergy is an immune response or reaction to substances that are usually not harmful. "However, nonsynonymous mutations were identified in the coding sequences of Cer1, Ttc39b, Ccdc171, Cntln, Adamtsl1, Haus6, Gm12551, and Dennd4c, but these genes do not have any prior documented associations with allergy, IgE, or asthma." (PMID 28696925, 2017).
fungal infection (1 paper, 2021). "In contrast, all the inoculated leaves of cer1-4 and cer3-6 already showed signs of fungal infection at 3 dpi, similar to the WT plants (data not shown)." (PMID 34804086, 2021).
hip fracture (1 paper, 2013). Traumatic or pathological injury to the hip in which the continuity of either the femoral head, femoral neck, intertrochanteric or subtrochanteric regions is broken. "When CER1 variations were correlated with the age of menopause, they were found to be independent while osteoporotic women with hip fracture were found to suffer menopause approximately 2.5 years earlier than the control group." (PMID 24138842, 2013).
lung carcinoma (1 paper, 2022). "Other genes, such as PTH2, TBR2, WNT7B, and CER1, either have similar effects shared with their homologues or have been independently reported to be associated with lung cancer at different omics levels." (PMID 35155435, 2022).
tumor (1 paper, 2007). "Following tumor growth in SCID mice, MCHs regularly lost defined regions in the 3p14-p21 area, designated as CER1 and FER." (PMID 17257397, 2007).
CER1 also shares sentences with these, for which no sentence is quoted: bladder cancer (2 papers); cancer (2); asthma (1); fracture (1); infection (1); mental retardation (1).